CRP (C-reactive protein)
Diseases named in the same sentence as CRP in open-access papers (continued):
Sharing a sentence is not in itself a finding about the gene and the disease.
atherosclerosis (1,286 papers, 2004 to 2026). A disease characterized by the build-up of fatty material and calcium deposition in the arterial wall resulting in partial or complete occlusion of the arterial lumen. "High-sensitivity C-reactive protein (hs-CRP), a marker of vascular inflammation, has been linked to atherosclerosis, but its utility in predicting multivessel disease in resource-limited settings remains uncertain." (PMID 42199589, 2026). "The mechanism of action by which CRP correlates with mortality risk have been shown to be linked to endothelial dysfunction leading to atherosclerosis, CVD-events and mortality." (PMID 41281897, 2025). "Elevated CRP levels are also associated with the development of subclinical atherosclerosis, as measured by CMIT." (PMID 40283183, 2025). "This critique notes rises in C-reactive protein and other biomarkers associated with atherosclerosis among the REDUCE-IT patients who received mineral oil, relative to patients randomized to EPA." (PMID 40974959, 2025). "From the data in the table, there was a positive correlation between the risk of developing atherosclerosis of large arteries and CRP levels (IVW:p = 0.003, OR=1.203,95% CI:1.066–1.358)." (PMID 40779499, 2025). "So, while CRP has been extensively studied as a marker of inflammation and cardiovascular risk, its specificity for atherosclerosis has been questioned." (PMID 39941424, 2025). "CRP is a significant cardiovascular risk factor and correlates in adults with atherosclerosis burden and cardiovascular events." (PMID 40217768, 2025). "Research consistently shows a marked link between cardiovascular incidents and hs-CRP levels exceeding 3 mg/L, when contrasted with those below 1 mg/L, the Multi-Ethnic Study of Atherosclerosis (MESA) reported a 50% increased risk at the 2 mg/L threshold." (PMID 40933377, 2025). "High-sensitivity CRP (hs-CRP) testing has emerged as a valuable tool for cardiovascular risk stratification, reinforcing the link between systemic inflammation and atherosclerosis." (PMID 40217801, 2025). "Sleep disturbances associated with somatic symptoms can elevate inflammatory markers (CRP, IL-6), contributing to vascular damage and atherosclerosis, thereby increasing stroke risk." (PMID 41583002, 2025). "Chronic inflammation drives the progression of atherosclerosis and other vascular diseases, with inflammatory markers such as C-reactive protein (CRP) and interleukin-6 (IL-6) linked to plaque instability and rupture." (PMID 39777701, 2025). "The present IVW analysis revealed that CRP increased the risk of atherosclerosis by 20.3% (OR=1.203)." (PMID 40779499, 2025). "CRP is commonly used to assess the pathologic inflammatory response and has been extensively studied in relation to thrombosis linked to atherosclerosis." (PMID 41036279, 2025). "CRP is associated with changes in the expression of adhesion molecules promoting disruption of the endothelium and development of atherosclerosis, leading to vascular dysfunction and neuronal damage." (PMID 39824904, 2025). "In T1D specifically, higher CRP concentrations have been linked to endothelial dysfunction, microvascular complications, and accelerated atherosclerosis." (PMID 41010714, 2025). "Positive MR analysis showed a causal relationship between CRP and amyloidosis and between CRP and atherosclerosis of large arteries." (PMID 40779499, 2025). "It is becoming clear that hs-CRP contributes significantly to the pathogenesis of atherosclerosis and is a significant cardiovascular risk factor." (PMID 40755626, 2025). "Research has shown that elevated CRP levels correlate with an increased risk of atherosclerosis, myocardial infarction, and other cardiovascular events." (PMID 40937117, 2025). "The potential explanation for the elevated CRP level is that subclinical vascular dysregulations, such as atherosclerosis, have been found to be associated with LOD." (PMID 40955269, 2025).
atherosclerosis (continued). "In fact, the expression of CRP has been associated with decreased LXA4 synthesis in foam cells in a rabbit model of atherosclerosis." (PMID 41369404, 2025). "In rheumatoid arthritis, for example, the magnitude and chronicity of the inflammatory response, as measured by C-reactive protein, have been linked to the progression of atherosclerosis." (PMID 40218272, 2025). "A recent study has found that hs-CRP and low-density lipoprotein cholesterol can predict the likelihood of CV events and death, and the risk of atherosclerosis can be reduced through active combination of lipid-lowering and anti-inflammatory therapy." (PMID 40041168, 2025). "High levels of TNF-α and interleukin-6 (IL-6) released from adipose tissue increase the risk of developing atherosclerosis (AS), stimulate the liver to produce more C-reactive protein (CRP), and increase blood pressure." (PMID 41226575, 2025). "The Dallas Heart Study found that the association between CRP and atherosclerosis was influenced by BMI, with a more significant relationship observed in non-obese individuals." (PMID 41343565, 2025). "One of the most widely utilized inflammatory biomarkers for determining the risk of atherosclerosis is high-sensitivity C-reactive protein (hs-CRP)." (PMID 40218291, 2025). "CRP, a downstream acute-phase reactant, is similarly elevated in OA and is associated with endothelial dysfunction and atherosclerosis progression, reinforcing its relevance to cardiovascular risk." (PMID 40688840, 2025). "KLF2 activation was predicted to activate CRP, which was subsequently associated with the enhanced progression of atherosclerosis and inflammation." (PMID 39125657, 2024). "C-reactive protein (CRP) is widely recognized as a crucial biomarker of inflammation implicated in the progression of atherosclerosis." (PMID 39253361, 2024). "The possible cause was that elevated CRP levels were directly related to the occurrence of atherosclerosis and the risk of plaque rupture." (PMID 38699426, 2024). "The pathophysiology of atherosclerosis is caused by the interaction of C-reactive protein (CRP), atherogenic LDL, and LOX-1." (PMID 39199251, 2024). "This enhanced sensitivity allows hs-CRP to assess the risk of chronic conditions, particularly cardiovascular diseases, where inflammation plays a subtle yet significant role in atherosclerosis development." (PMID 38983990, 2024). "CRP levels are associated not only with inflammation but also with endothelial dysfunction and atherosclerosis progression, and the link is supported by the oxidative stress burden." (PMID 38398435, 2024). "The s-JMJD6-Ab levels were closely associated with some inflammation indicators, such as C-reactive protein and intima–media thickness (an atherosclerosis index)." (PMID 38732153, 2024). "Representative keywords include Porphyromonas gingivalis, inflammation, risk, oral health, C-reactive protein, atherosclerosis risk, and endothelial dysfunction." (PMID 39610974, 2024). "CRP is a common inflammatory marker, and elevated levels of CRP areclosely associated with increased risk of atherosclerosis and cardiovascular events." (PMID 38933362, 2024). "The increase in pro-fibrotic SP1 in macrophages of the high-CRP group is likely associated with increased fibrosis related to atherosclerosis." (PMID 39737187, 2024). "On the other hand, IL-6 in the liver stimulates the production of C-reactive protein (CRP), the main acute-phase inflammatory molecule associated with childhood obesity, as well as atherosclerosis and cardiac events." (PMID 38133765, 2024). "Nitric oxide (NO) released from endothelial cells is inhibited by CRP causing the severe atherosclerosis and loss of vascular flexibility." (PMID 38961103, 2024). "High-sensitivity C-reactive protein (CRP) and fibrinogen have been demonstrated to be associated with atherosclerosis." (PMID 39227703, 2024).
atherosclerosis (continued). "This is similar to another study that found increased levels of CRP strongly predict thrombotic complications of atherosclerosis and are associated with CVD risk." (PMID 39734983, 2024). "Further, inflammation is a well-known risk factor for the development of atherosclerosis, with elevated CRP levels being strongly linked to the onset of PAD." (PMID 39429407, 2024). "Inflammatory markers such as CRP and IL-6, linked to H. pylori infection, play significant roles in the development of atherosclerosis and CVDs." (PMID 39202269, 2024). "IL-6 and CRP are widely studied inflammatory markers and have been found to be associated with atherosclerosis plaque development, especially in elderly stroke and transient cerebral ischemia patients." (PMID 37611898, 2024). "Key research hotspots in this field include Porphyromonas gingivalis, inflammation, risk, oral health, C-reactive protein, atherosclerosis risk, and endothelial dysfunction." (PMID 39610974, 2024). "Elevated CRP levels have been associated with major cardiovascular events in individuals with coronary artery disease and atherosclerosis burden." (PMID 39125344, 2024). "The association of DM and CRP with atherosclerosis and CAD is an undeniable fact, and studies are showing that these 2 variables are associated with CAD prevalence." (PMID 39597855, 2024). "The direct pathogenic role of CRP in the process of atherosclerosis and plaque formation is well-known even in women who are healthy but have a history of smoking." (PMID 38248862, 2024). "CRP and its high-sensitivity counterpart (hs-CRP) haveemerged as valuable biomarkers in cardiovascular surgery, extending beyond theirestablished association with systemic inflammation and atherosclerosis." (PMID 39484111, 2024). "Nontraditional risk factors, such as extra-articular manifestations, swollen joint count, autoantibody levels, and C-reactive protein (CRP) levels, have been implicated in accelerated atherosclerosis." (PMID 36913212, 2023). "The guideline has recommended that LDL− C and CRP are independent risk factors for atherosclerosis and play important roles in the primary and secondary prevention of atherosclerosis." (PMID 37986011, 2023). "Serum CRP concentrations are associated with atherosclerosis progress and are used as a prognostic indicator of cardiovascular incidents." (PMID 37998729, 2023). "Recently, a Mendelian randomization study conducted to clarify the role of CRP in predisposition to atherosclerosis was unable to find a direct correlation between genetic variants of CRP and coronary heart disease (CHD) risk." (PMID 39554800, 2023). "Elevated levels of CRP have been independently associated with the progression of atherosclerosis in humans." (PMID 37108035, 2023). "The IVW method revealed a direct association between increased circulating CRP levels and increased risk of atherosclerosis by 17% (OR = 1.17 [1.05–1.30], p = 0.005) in Approach 1, but not in Approach 2 (OR = 1.10 [0.96–1.26], p = 0.164)." (PMID 37298077, 2023). "Serum CRP levels have also been shown to indicate the risk of cardiovascular disease, owing to their role as inflammatory markers in atherosclerosis, coronary artery disease, and peripheral arterial disease." (PMID 39554800, 2023). "CRP is the widely used inflammatory biomarker linked to underlying atherosclerosis and future CV disease." (PMID 37252112, 2023). "Exploring molecular pathways underlying atherosclerosis, interest ininflammatory biomarkers and targeted therapy has shifted upstream from CRP." (PMID 39076864, 2023). "Each standard deviation increase in hs-CRP concentration increases the risk by 45%, so the level of hs-CRP can be applied to distinguish low-risk from high-risk for atherosclerosis and cardiovascular disease." (PMID 36873405, 2023). "There have been reports suggesting a potential causal role for CRP in the development of atherosclerosis." (PMID 37958528, 2023).
atherosclerosis (continued). "The cholesterol content of a wide range of lipoprotein and apolipoproteins associate with measures of atherosclerosis, blood pressure, CRP, and CHD, with a subset affecting HF, T2DM, AD and IBD risk." (PMID 36670186, 2023). "Inflammation plays an important role in all stages of atherosclerosis, meaning that a decreased albumin level and increased CRP level are associated with the chronic nature of the disease." (PMID 37762611, 2023). "And association, atherosclerosis, c-reactive protein, events, inflammation, and unstable angina were shown in the yellow one." (PMID 37576112, 2023). "It has been shown that elevated C-reactive protein, interleukin-1, and tumour necrosis factor are associated with pro-inflammatory and atherogenic atherosclerosis, and mononuclear phagocytes can advance the progression of all stages of atherosclerosis." (PMID 37711556, 2023). "Since CRP mainly reflects themechanism underlying atherosclerosis, IL-6 is causally involved in this process.Experimental studies have shown that IL-6 contributes to initiation andprogression of atherosclerotic plaque." (PMID 39076864, 2023). "Lpa is shown to be an indicator of premature atherosclerosis, CRP is an inflammatory biomarker and is associated with increased risk of CAD Fibrinogen and Factor VII are also shown to be associated with CAD." (PMID 36874455, 2023). "The role of CRP as a predictive marker of atherosclerosis through its association with IMT has already been well documented." (PMID 36983201, 2023). "According to a multi-ethnic atherosclerosis cohort study, a diet rich in fruits, vegetables, whole grains, and fish had an inverse association with inflammatory indicators, including CRP and E-selectin." (PMID 38087232, 2023). "There is copious data supporting the association between high hs-CRP levels and atherosclerosis severity—expressed either as mortality and risk or as surrogate markers such as triglyceride concentration or body mass index." (PMID 36553147, 2022). "Recent reports indicated that high sensitivity C-reactive protein (hsCRP) concentration can reflect active systemic inflammation and independently associated with the severity of atherosclerosis." (PMID 36032093, 2022). "Hypercholesterolemia is associated with increases in AGE,oxidative stress [AGE/sRAGE (soluble receptor for AGE)] and C-reactive protein,and decreases in the sRAGE, which are known to be implicated in the developmentof atherosclerosis." (PMID 39077184, 2022). "As briefly mentioned, a previous population-based study found an association between carotid plaques and low DLCO, also after adjusting for C-reactive protein and traditional atherosclerosis risk factors." (PMID 35263363, 2022). "C-reactive protein (CRP) is a known serum marker of inflammation, and it has been shown to be associated with atherosclerosis." (PMID 35448062, 2022). "Several CRP gene single nucleotide polymorphisms (SNPs) influence the plasma CRP levels in CVDs and previous studies have aimed to elucidate the role of SNPs in the CRP locus, CRP levels and early signs of atherosclerosis." (PMID 35428187, 2022). "Clinical studies have indicated that inflammation indicator CRP is a risk biomarker of atherosclerosis, which can mediate atherosclerosis at different stages." (PMID 36699920, 2022). "The C-reactive protein (CRP) is an important biomarker for atherosclerosis and single nucleotide polymorphisms (SNPs) in the CRP locus have been associated with altered CRP levels and associated with risk for cardiovascular disease." (PMID 35428187, 2022). "There is evidence that with increased PM2.5 exposure, various inflammatory markers and immune parameters associated with atherosclerosis are reported to be elevated, including high-sensitivity CRP, plasma fibrinogen, IL-6, immunoglobulin (Ig)G, IgM, and IgE." (PMID 36082127, 2022).
atherosclerosis (continued). "Inflammation can be associated with all stages in the development and progression of atherosclerosis; in fact, elevated values of certain inflammatory markers, including IL-6 and CRP have been associated with adverse prognosis in patients with atherosclerosis." (PMID 36078455, 2022). "CRP is an inflammatory biomarker associated with arterial calcification and atherosclerosis and has been considered an independent risk factor for cardiovascular events." (PMID 36309659, 2022). "A high level of CRP is also a strong predictor of atherosclerosis and is closely associated with plaque instability histologically and clinically." (PMID 35178859, 2022). "Quercetin systemically decreased expression of human CRP and cardiovascular risk factors and locally in aorta showed anti-proliferative effect resulting in attenuation of atherosclerosis." (PMID 35120520, 2022). "HBC infection was negatively correlated with systemic inflammation evaluated by C-reactive protein, an independent risk factor for atherosclerosis." (PMID 35979042, 2022). "The LDL-C, Hcy, and CRP levels exhibited statistical differences between the healthy controls and patients with atherosclerosis and were also associated with serum DANCR expression levels." (PMID 35235755, 2022). "Because of its complex pro-inflammatory and anti-inflammatory effects, CRP has been shown to have a clear correlation with chronic inflammatory changes in atherosclerosis and is an important risk factor for cardiovascular and cerebrovascular diseases." (PMID 36457873, 2022). "Some studies have highlighted that during chronic infections and inflammation, elevated levels of the pro-inflammatory cytokines interleukin (IL)-6 and C-reactive protein (CRP) are associated with subclinical atherosclerosis." (PMID 35819948, 2022). "Proteomics analysis revealed that deposition of mCRP in the aneurysmal wall along with high serum CRP level is associated with various signaling pathways related to complement activation, atherosclerosis, and thrombogenesis." (PMID 34428207, 2021). "Incidence rates (95% CI) and hazard ratios (95% CI) for the association of CRP, IL-6 and fibrinogen with incident atrial fibrillation: The multi-ethnic study of atherosclerosis (2000–2015)." (PMID 33765041, 2021). "The majority of the unexplained increase in CRP levels in peritoneal dialysis patients is associated with atherosclerosis." (PMID 34532198, 2021). "Hs-CRP, as a sensitive indicator of inflammation, has been proved to be not only the independent risk factor of cardiovascular disease but also mediator of atherosclerosis through IL-1-to-IL-6-to-CRP signalling pathway by CANTOS trial." (PMID 35082785, 2021). "Lp(a), C-reactive protein, circulating immune complexes, and the neutrophil-to-lymphocyte ratio are associated with stenotic atherosclerosis of different vascular beds." (PMID 33513851, 2021). "Over the past few decades, emerging evidence has shown that serum CRP is associated with the risk of several chronic conditions, such as cardiovascular disease, atherosclerosis and cancer." (PMID 35070979, 2021). "Circulating levels of CRP have been suggested to reflect the extent and severity of general atherosclerosis, and to relate to the risk of plaque rupture and vascular thrombosis." (PMID 34649504, 2021). "Elevated levels of serum CRP have been associated with an increased risk of several chronic conditions, such as cardiovascular disease, atherosclerosis, and cancer." (PMID 35070979, 2021). "Second, higher CRP concentrations were observed among individuals at increased risk of cardiovascular diseases, such as atherosclerosis, stroke, and myocardial infarction." (PMID 33921787, 2021). "Treatment with low-doses of the anti-inflammatory drug methotrexate failed to reduce the levels of IL-1β, IL-6 or C-reactive protein (CRP), and CV events in patients with stable atherosclerosis and high CV risk." (PMID 34501271, 2021).